MTOR (mechanistic target of rapamycin kinase)
Diseases named in the same sentence as MTOR in open-access papers (continued):
Sharing a sentence is not in itself a finding about the gene and the disease.
cardiomyopathy (continued). "Both of our in vitro and in vivo studies consistently demonstrated that mTOR inhibition cannot exert therapeutic effects for RagCS75Y cardiomyopathy." (PMID 34071043, 2021). "The MTOR-Tg mice show attenuated inflammatory response and cardiomyopathy upon left ventricular pressure overload induced by transverse aortic constriction." (PMID 31884871, 2020). "Taken together, these data suggest that mTOR is required for Gfat1-mediated cardiomyocyte growth, and suppression of mTOR can rescue cardiomyopathy due to persistent elevation of Gfat1 in vivo." (PMID 32286306, 2020). "Evidence shows that mTOR has a significant function in promoting cardiac diseases, including cardiomyopathy, myocardial ischemic injury and myocardial fibrosis." (PMID 32269242, 2020). "Possibly, dysregulated mTOR signaling is a common pathologic event among cardiomyopathies of different etiology, as suggested by other reports of studies in mammalian cardiomyopathy models, and mTOR inhibition is a common therapeutic strategy." (PMID 33329049, 2020). "Accumulating evidence suggests that mTOR signaling can also be manipulated to benefit pathological cardiomyopathies." (PMID 31492659, 2019). "Involvement of mTOR signaling in laminopathic adipose tissue defects has been also explored in Lmna−/− mice used to study cardiomyopathy and muscle dystrophy." (PMID 30781376, 2019). "Because mTOR signaling is vital for proteostasis, and mTOR is a known therapeutic target for several types of cardiomyopathies, we focused on mTOR signaling experimentally." (PMID 31492659, 2019). "This was further supported by the fact that the mTOR activator 3BDO effectively nullified GLP-1 agonist-offered beneficial response against glucose toxicity, favoring a permissive role for mTOR in GLP-1 analogue-offered protection against cardiomyopathy." (PMID 29849901, 2018). "Our in vivo studies suggest that the cardioprotective effect of FoxO3 may lie in the activation of autophagy and depend on the mTOR pathway in DOX‐induced cardiomyopathy." (PMID 40785055, 2025). "Besides, FoxO3 modulated DOX cardiomyopathy associated with the autophagy‐related gene LC3B, p62 and Beclin 1, as well as mTOR signalling in vivo and in vitro." (PMID 40785055, 2025). "Furthermore, RNA-seq analysis pointed at significant differences in the mTOR and autophagy pathways in cardiomyopathy from the T1DM versus T2DM models." (PMID 36674648, 2023). "Current studies revealed that the AKT/mTOR pathway is responsible for DOX-induced cardiomyopathy." (PMID 35204799, 2022). "Postnatal treatment of NS-ML mouse models with inhibitors of the PI3K/mTOR/AKT pathway or with the tyrosine kinase inhibitor dasatinib reversed cardiomyopathy phenotypes, and treatment of a NS-ML patient with the mTOR inhibitor everolimus provided clinical benefit." (PMID 35178568, 2022). "The observation was initially surprising, because mTOR inhibition has been shown to have broad applicability to many types of cardiomyopathies and mTORC1 signaling was obviously activated in our RagCS75Y cardiomyopathy models." (PMID 34071043, 2021). "To develop effective therapy for RagCS75Y cardiomyopathy, we first assessed whether mTOR inhibition exerts therapeutic effects in both in vitro and in vivo models." (PMID 34071043, 2021). "Further mechanistic studies and drug development efforts of mTOR-based therapy are needed, which could benefit a broad spectrum of cardiomyopathies with different etiologies." (PMID 31492659, 2019). "Whether mTOR inhibition is effective in ameliorating the BAG3 cardiomyopathy subtype remains untested." (PMID 31492659, 2019). "However, the relationship between FoxO3 and the mTOR signalling pathway in DOX‐induced cardiomyopathy remains unclear." (PMID 40785055, 2025). "Therefore, tfeb is a promising downstream candidate gene that could recapitulate the cardioprotective effects of mTOR inhibition on the bag3e2/e2 cardiomyopathy model via repairing dysregulated proteostasis." (PMID 40922543, 2025).
cardiomyopathy (continued). "Therefore here, we tested the involvement of mTOR in the development of cTnI-G203S cardiomyopathy." (PMID 36596888, 2023). "However, the connection between RRM2 and the AKT/mTOR signaling pathway in DOX-induced cardiomyopathy remains unclear." (PMID 35204799, 2022). "Furthermore, cardiomyopathy was associated with disturbed protein homeostasis as demonstrated by increased markers of UPR/ER stress, an increase in polyubiquitinated proteins and dysregulated autophagy-associated mTOR signaling." (PMID 35743185, 2022). "We asked whether suppression of mTOR might rescue the cardiomyopathy phenotype." (PMID 32286306, 2020). "We assumed that miR-1246 might target UBE2C, TNNT1, TRAIP, and UCHL1 during the regulation of ubiquitin-mediated proteolysis, glycosaminoglycan binding, DNA metabolism, the PI3K–Akt–mTOR signaling pathway, the neurotrophin and cardiomyopathy signaling pathway, and the MAPK signaling pathway." (PMID 33050659, 2020). "On the other hand, it is also possible that mTOR inhibition attenuates a common pathological event that is shared among different types of cardiomyopathy, as suggested by its cardioprotective effects on several subtypes of cardiomyopathies in both zebrafish and mouse." (PMID 31492659, 2019). "Last, we tested whether genetic inhibition of mTOR is cardioprotective for bag3 cardiomyopathy." (PMID 31492659, 2019). "For example, rapamycin, an autophagy flux activator through mTOR inhibition, mitigates DOX-evoked cardiomyopathy in mice." (PMID 38931349, 2024). "In previous studies, our group found that certain drugs reduce the lipotoxicity of cardiomyocytes through mTOR/HIF-1α dilution and can also resist cardiomyopathy through ROS/p38/JNK coupling." (PMID 39273228, 2024). "There is extensive evidence for both mTOR and TFEB as therapeutic targets for cardiomyopathies of different etiology." (PMID 34071043, 2021). "In cardiomyopathy rat models, lncRNA H19 silenced DIRAS3 expression, promoted MTOR phosphorylation and inhibited autophagy in cardiomyocytes." (PMID 32301281, 2020). "This review focuses on mTOR-dependent pathogenetic events identified in Emery-Dreifuss muscular dystrophy, LMNA-related cardiomyopathies, Hutchinson-Gilford Progeria, mandibuloacral dysplasia, and type 2 familial partial lipodystrophy." (PMID 30781376, 2019). "In summary, we concluded that TFEB activation, but not mTOR inhibition, is therapeutic to RagCS75Y cardiomyopathy." (PMID 34071043, 2021). "Whether mTOR, TFEB, or both are effective therapeutic targets for RagCS75Y cardiomyopathy remains untested." (PMID 34071043, 2021). "Furthermore, other signaling cascades, AKT/mTOR, TGF-β, CTGF and p38α, are involved in the pathogenesis of the EDMD cardiomyopathy." (PMID 29619865, 2018). "Based on our research, overexpression of FoxO3 enhances autophagy, inhibits oxidative stress and mTOR activation in the doxorubicin model; we propose that FoxO3 initiates autophagy, resulting in a favourable outcome that mitigates the effects of DOX‐induced cardiomyopathy." (PMID 40785055, 2025). "Therefore, mTOR inhibition failed to restore nuclear translocation of TFEB or ameliorate cardiomyopathy in RRAGC-mutant-related dilated cardiomyopathy." (PMID 37749558, 2023). "However, the association between damage of the cardiac contractile unit—desmin and neighboring sarcomere—and the iNOS/mTOR/TIMP-1/collagen axis of fibrosis in rats with T2DM-induced cardiomyopathy has not been previously investigated." (PMID 35625721, 2022). "However, mTOR inhibition failed to ameliorate cardiac phenotypes in the RagCS75Y cardiomyopathy models, concomitant with a failure to promote TFEB nuclear translocation." (PMID 34071043, 2021).
cardiomyopathy (continued). "Conversely, alcohol-mediated inhibition of mTOR/S6K1, down-regulation of INS receptor and growth-inhibitory mir-200 family, and upregulation of mir-212 that promotes fetal gene program may exacerbate CRS-related cardiomyopathy." (PMID 21977024, 2012). "However, given that RagCS75Y cardiomyopathy could be ascribed to the increased Rags–TFEB binding that is independent of mTOR signaling, mTOR inhibition is also possible not to exert therapeutic benefits." (PMID 34071043, 2021). "A primary pathological step of RagCS75Y cardiomyopathy is defective mTOR–TFEB signaling, which can be corrected by TFEB overexpression, but not mTOR inhibition." (PMID 34071043, 2021).
cognitive decline (50 papers, 2012 to 2026). "Our data points towards a consumptive loss of molecules of the mTOR signaling cascade with time in animals with hyperactive mTOR over lifetime leading to premature cognitive decline." (PMID 39192595, 2024). "Accordingly, topiramate’s ability to stimulate the hippocampal autophagy events and the associated AMPK/mTOR cascade is, at least partly, engaged in rescuing the cognitive decline associated with cadmium intoxication." (PMID 37765022, 2023). "mTOR is also implicated in cognitive decline during normal aging, and Rapamycin administration has been able to preserve brain function and mitigate cognitive decline in AD by increasing autophagy and reducing amyloid-beta and tau pathogenic proteins." (PMID 36523957, 2022). "In summary, we show that mTOR drives cerebrovascular and neuronal dysfunction associated with cognitive decline during normative aging in the rat." (PMID 31693798, 2020). "Numerous studies have demonstrated a deregulation of mTOR pathway in DS and have linked the alterations of mTOR pathway to cognitive decline, AD, and AD‐like dementia in DS." (PMID 30768754, 2019). "Increased Akt activation and mTOR phosphorylation have been reported in brains of AD patients, which is associated with a disrupted clearance of Aβ and tau, synaptic loss, and cognitive decline." (PMID 31798451, 2019). "Inhibition of autophagy by overactivated mTOR causes the accumulation of Aβ peptides and p-tau, resulting in synaptic loss, neuron death, and cognitive decline in AD brains." (PMID 28561773, 2017). "In AD brains, mTOR is hyperactivated, resulting in the inhibition of autophagy, which appears to cause the accumulation of Aβ and p-tau, synaptic loss, and cognitive decline." (PMID 28561773, 2017). "Here, we found that a substantial decrease of IEG expression during memory challenge and molecularly, an increase of markers of neurodegeneration and a decrease of expression of components of the mTOR/Akt1 signaling cascade are associated with the cognitive decline in aging Tsc2+/− animals." (PMID 39192595, 2024). "Our findings demonstrate that activation of the BDNF/TrkB/mTOR signalling pathway can mitigate the cognitive decline induced by Rep lido in aged mice." (PMID 41318982, 2025). "Inhibiting mTOR in mouse models has been found to alleviate cognitive decline and pathological features of AD." (PMID 38999445, 2024). "Our data shows that a continuously increased mTOR activity in a Tsc2+/− animal model with time leads to a substantial downregulation of molecules of the mTOR pathway and to premature cognitive decline." (PMID 39192595, 2024). "In order to further validate the influence of Akt/mTOR/IGF2 downregulation on the cognitive decline phenotype, we investigated if IGF2 injection can rescue memory consolidation in aged Tsc2+/− mice." (PMID 39192595, 2024). "An increasing body of studies has connected changes in mammalian target of rapamycin (mTOR) and serine/threonine kinases to aging-induced cognitive decline and the development of AD." (PMID 37450931, 2024). "Many studies have shown that the phosphorylation of PI3K/AKT/mTOR reduces the degree of brain tissue damage and cognitive decline, and insufficient phosphorylation leads to an inflammatory cascade reaction exacerbating necrosis and apoptosis." (PMID 37517091, 2023). "Activated mTOR in lymphocytes of AD patients correlates with cognitive decline, suggesting a parallel mTOR activation in brain." (PMID 37457922, 2023). "Recent studies reported that mTOR signaling pathway links to the aging-dependent cognitive decline and acts as a critical effector of cerebrovascular dysfunction in AD." (PMID 32751716, 2020). "A number of mTOR-autophagy modulators have been shown to have positive effects on cognitive decline." (PMID 32372981, 2020).
cognitive decline (continued). "Several studies have shown that in AD early stages, abnormal and continuous activation of PI3K/Akt/mTOR signaling occurs, with increased phosphorylation of mTOR, contributing to disease progression and cognitive decline." (PMID 31798451, 2019). "Our treatment supports the pathological role of aberrant mTOR/autophagy axis in DS mice and propose/confirm mTOR as a valuable target to prevent/slow the development of AD-related cognitive decline in DS as well as in the general population." (PMID 30410750, 2018). "Modulating mTOR activity therefore provides an attractive avenue to discover new therapies to attenuate diabetic-related cognitive decline and prevent diabetic encephalopathy and AD." (PMID 28801605, 2017). "Nevertheless, IMF was shown to create a more robust and steady inhibition of mTOR-accelerated aging and cognitive decline when compared to CCR." (PMID 27429752, 2016). "However, chronic PI3Kγ/mTOR-driven signaling results in neuroinflammation and white matter degeneration alongside cognitive decline." (PMID 40806341, 2025). "Our data suggests that early inhibition of mTOR might similarly be able to prevent overburdening of the synaptic mTOR signaling cascade and thereby abrasion of local protein synthesis and cognitive decline could be delayed in Tsc2+/− animals." (PMID 39192595, 2024). "SGLT2 inhibitors also reduce brain damage and cognitive decline through different aspects of brain protection, such as mitochondrial function, synaptic plasticity, acetylcholinesterase activity, amyloid plaques, and modulation of the mTOR pathway." (PMID 39767639, 2024). "Additionally, based on animal studies, administration of mTOR inhibitor drugs seems to be a potential pharmaceutical approach in patients with AD to ameliorate cognitive decline." (PMID 37721413, 2024). "Clinical strategies targeting neuroinflammation or the mTOR signaling cascade may provide promising therapeutic approaches for treating cognitive decline and AD progression in individuals with HL." (PMID 39725872, 2024). "Importantly, interventions that improve metabolic function, such as caloric restriction or drugs that target insulin or mTOR signaling, delay the onset of aging-related cognitive decline." (PMID 35406051, 2022). "Activation of PI3K/Akt/mTOR increased amyloid precursor protein synthesis and deposition, in part by inhibiting autophagy mediated Aβ clearance, while restoration of autophagy reverses cognitive decline and ameliorated Aβ pathology." (PMID 35604830, 2022). "The mammalian target of rapamycin (mTOR) and ribosomal S6 protein kinase (p70S6K) are serine/threonine kinases that play key roles in the regulation of protein synthesis and degradation, age-dependent cognitive decline, and pathogenesis of AD." (PMID 35197970, 2022). "In the present studies, we sought to determine whether mTOR plays a role in cerebrovascular dysfunction and cognitive decline during normative aging in rats." (PMID 31693798, 2020). "Chronic mTOR attenuation via rapamycin preserved cerebrovascular function and microvascular integrity, improved synaptic integrity and neuronal network activation throughout aging, and negated age-related cognitive decline in aged rats." (PMID 32756010, 2020). "Activation of mTOR increased amyloid precursor protein synthesis and deposition, in part by inhibiting autophagy-mediated Aβ clearance, while restoring autophagy through inhibition with rapamycin reversed cognitive decline and ameliorated Aβ pathology." (PMID 30684442, 2019). "The mTOR pathway influences neuronal development and plasticity, and its dysfunction in the aging brain may contribute to cognitive decline." (PMID 30684442, 2019). "Moreover, TMAO promotes neuron senescence, damages synapses, down‐regulates the expression levels of both synaptic plasticity‐related proteins and the mTOR signalling pathway and therefore deteriorates brain aging and cognitive decline in mice." (PMID 29749694, 2018).